ENG (endoglin)
Diseases named in the same sentence as ENG in open-access papers (continued):
Sharing a sentence is not in itself a finding about the gene and the disease.
Arthritis (1 paper, 2007). Inflammation of a joint. "Whereas this study provides the first report concerning the expression of TGFBR1 in human arthritis, the type II receptor and endoglin (a receptor for TGF-β1 and 3) have been reported to be more strongly expressed in RA SM than in OA SM or normal SM, showing the relevance of TGF-β-signaling in RA." (PMID 17594488, 2007).
blepharitis (1 paper, 2021). Inflammation of the eyelids near the eyelashes. "Mice with blepharitis that were heterozygous in the HHT genes endoglin (ENG) had more pronounced hemorrhagic lesions in the eyelids." (PMID 34445743, 2021).
capillary hemangioma (1 paper, 2023). A common hemangioma characterized by the presence of capillary-sized vascular channels without prominent epithelioid endothelial cells. "Endoglin is also highly expressed in the head and neck tumors of vascular origin, such as capillary hemangiomas and juvenile nasopharyngeal angiofibroma." (PMID 36844233, 2023).
cardiac hypertrophy (1 paper, 2018). "This phenotype is accompanied by trabecular compaction defects including absence of papillary muscle coalescence, deep protrusions of Endoglin+ cells resulting in endocardial islets, hypoplasia of the PF network, extensive subendocardial fibrosis and cardiac hypertrophy." (PMID 29979676, 2018).
cerebral artery occlusion (1 paper, 2022). "To validate these in vitro data, we additionally examined endoglin expression in an intraluminal monofilament model of permanent and transient middle cerebral artery occlusion in mice." (PMID 35806090, 2022).
chorioamnionitis (1 paper, 2023). A morphologic finding indicating inflammation of the fetal sac membranes. "In addition, levels of endoglin, a component of the TGF-β receptor complex, are increased in the amniotic fluid of women with chorioamnionitis and overexpression of endoglin in the amniotic fluid of pregnant rats causes decreased alveolarization and vascularization in the rat pups." (PMID 36625900, 2023).
chronic myelocytic leukemia (1 paper, 2020). "In addition, Endoglin was shown to be expressed in the cell lines HL-60 and KG-1a, which were derived from individuals with AML, in the cell line EM-3 derived from a patient with chronic myelocytic leukemia (CML) and in the B-lymphoblastoid cell lines 3104 and 3161." (PMID 33287465, 2020).
depression (1 paper, 2022). "Particularly relevant, given the important role of B2RAN2 (highly similar to vanin-1) and endoglin in oxidative stress and the immune system, they may play roles in depression, being suggested as potential candidate biomarkers to distinguish between MDD and BP." (PMID 35628270, 2022).
emphysema (1 paper, 2012). "The changing expression of SMAD6 and SMAD1, their localization predominantly to vascular endothelial cells, and the roles of ACVRL1 and ENG in angiogenesis support the hypothesis of aberrant tissue remodeling in the lung vasculature during emphysema pathogenesis." (PMID 22937864, 2012).
glomerular diseases (1 paper, 2017). "Moreover, numerous studies have demonstrated the involvement of the transforming growth factor beta (TGFβ), its receptors, for example Endoglin, (ENG) and members of the Notch receptor family play a key role in pathogenesis of glomerular diseases." (PMID 28859090, 2017).
glomerulosclerosis (1 paper, 2020). A hardening of the kidney glomerulus caused by scarring of the blood vessels. "The finding suggest that endoglin might also play a role in mesangial extracellular matrix production, and thereby, in the development of glomerulosclerosis." (PMID 33081058, 2020).
hepatopathy (1 paper, 2013). "We then aimed to directly compare the diagnostic performance of TIMP-4, Endoglin and TE as novel diagnostic markers for CFLD to clinical markers of hepatopathy." (PMID 23516586, 2013).
IgA nephropathy (1 paper, 2022). "First, we stained paraffin-embedded serial sections of renal biopsies from patients with CAD, DN, FSGS and IgA nephropathy for endoglin and Sirius Red, which indicates the presence of collagen and measured the positively stained areas in the interstitium." (PMID 36614087, 2022). "When CAD, DN, FSGS and IgA nephropathy were pooled, the endoglin-positive interstitial area had a significant inverse correlation with the eGFR (p < 0.001)." (PMID 36614087, 2022). "Evidence for this comes from the two largest cohorts, scilicet IgA nephropathy and CAD, which also individually showed a significant correlation between the endoglin and Sirius Red-positive area." (PMID 36614087, 2022). "In this study, we measured renal endoglin expression in biopsy samples obtained from patients with different types of CKD, i.e., IgA nephropathy, FSGS, DN and patients with chronic allograft dysfunction (CAD)." (PMID 36614087, 2022).
intracerebral hemorrhage (1 paper, 2023). A cerebrovascular disorder characterized by bleeding into one or both cerebral hemispheres including the basal ganglia and the cerebral cortex. "Across subtypes, the highest hit rate (HR) was intracerebral hemorrhage (ICH, 7/18 = 38.9%), particularly with the etiological subtype of structural vasculopathy (4/4 = 100%, PVs in ENG, KRIT1, PKD1, RNF213); followed by ischemic small vessel disease (SVD, 15/48 = 31.3%; PVs in NOTCH3, HTRA1, HBB)." (PMID 36580209, 2023).
intracranial aneurysm (1 paper, 2015). "In total, there are five MS genes related to intracranial aneurysm (CASP3, ENG, TIMP1, TIMP2, and TIMP3)." (PMID 26486520, 2015).
invasive carcinoma (1 paper, 2009). A carcinoma that is not confined to the epithelium, and has spread to the surrounding stroma. "The significant increase in the percentage of specimens expressing endoglin in both high-grade in situ and invasive carcinomas indicates increases in actively proliferating vessels participating in angiogenesis." (PMID 19623180, 2009). "In contrast to CD31 staining, endoglin was not expressed in normal breast ECs, but was expressed by ECs in 17% of UDH cases, 19% of ADH cases, 21% and 44% of DCIS cases (low/intermediate grade and high grade, respectively) and in 84% of invasive carcinomas." (PMID 19623180, 2009).
leukopenia (1 paper, 2017). "Investigators report leukopenia, increased risk of infection and impaired endoglin upregulation in activated monocytes of HHT1 patients." (PMID 29253907, 2017). "Flow cytometric analysis of blood samples at baseline revealed that the mice did not display any leukopenia because of endoglin heterozygosity (gating strategy provided in S7A and S7B Fig)." (PMID 29253907, 2017).
nephritis (1 paper, 2021). Inflammation of renal tissue. "Last, the inhibition of another anti-angiogenic factor such as Endoglin has been shown to promote intussusceptive angiogenesis in experimental nephritis." (PMID 34359843, 2021).
neuropathic pain (1 paper, 2025). Chronic pain caused by damage to nerve fibers. "We then examined the expression of endoglin in the peripheral blood of rats subjected to spinal nerve injury (SNI), which serves as an animal model for neuropathic pain." (PMID 41030313, 2025).
osteoporosis (1 paper, 2020). A condition of reduced bone mass, with decreased cortical thickness and a decrease in the number and size of the trabeculae of cancellous bone (but normal chemical composition), resulting in increased fracture incidence. "Although SERMs are primarily used to prevent or treat osteoporosis, they have shown to be effective in HHT compensating partially, the haploinsufficiency present in HHT patients by increasing the protein levels of endoglin and ALK1." (PMID 32517280, 2020).
Pain (1 paper, 2025). An unpleasant sensory and emotional experience associated with actual or potential tissue damage, or described in terms of such damage. "Our findings indicate that endoglin can improve the inflammatory response associated with chronic neuropathic pain." (PMID 41030313, 2025).
pancreatic neuroendocrine tumor (1 paper, 2016). Pancreatic endocrine tumor, also known as pancreatic neuroendocrine tumor (PNET), describes a group of endocrine tumors originating in the pancreas that are usually indolent and benign, but may have the potential to be malignant. "Here we investigate the interaction of two such receptors, ALK1 and endoglin, in pancreatic neuroendocrine tumors (PanNET)." (PMID 27741515, 2016).
papilloma (1 paper, 2021). A benign epithelial neoplasm that projects above the surrounding epithelial surface and consists of villous or arborescent outgrowths of fibrovascular stroma. "We observed increased density of endoglin+ cells in Zfp36ΔEP papillomas compared with Zfp36fl/fl samples, indicating that the absence of TTP in tumor cells promoted angiogenesis." (PMID 33497366, 2021). "To evaluate angiogenesis and neovascularization of Zfp36fl/fl and Zfp36ΔEP papillomas, we performed immunofluorescent staining for VE-Cadherin (an endothelial marker) and endoglin, a transmembrane glycoprotein expressed on activated vascular endothelial cells." (PMID 33497366, 2021).
paraganglioma (1 paper, 2023). A benign or malignant neoplasm arising from paraganglia located along the sympathetic or parasympathetic nerves. "They reported a significantly higher expression of endoglin in paraganglioma tissues than in the control lung tissue, whereas VEGF level was similar in both tissues." (PMID 36844233, 2023). "Endoglin is also highly expressed in non-malignant richly vascularized tumors, including paragangliomas and juvenile angiofibromas." (PMID 36844233, 2023).
paroxysmal nocturnal haemoglobinuria (1 paper, 2022). "For the detection of endothelial EVs, we selected endoglin (CD105) as a marker which was successfully utilized for the demonstration of increased plasma endothelial EVs in paroxysmal nocturnal haemoglobinuria." (PMID 35628959, 2022).
pericardial effusion (1 paper, 2014). Fluid collection within the pericardial sac, usually due to inflammation. "Correspondingly, Endoglin-null embryos with heart valve and septation defects do not progress beyond E10.5, fail to form mature blood vessels in the yolk sac, lack trabeculae and exhibit small hearts with an absence of a defined right ventricle and pericardial effusion." (PMID 26090377, 2014).
peripheral nerve injury (1 paper, 2025). Injury to a peripheral nerve. "Specifically, intrathecal administration of exogenous endoglin significantly inhibited the activation of microglia and the expression of inflammatory factors in the dorsal horn of the ipsilateral spinal cord induced by SNI, while also reducing peripheral nerve injury-induced hyperalgesia." (PMID 41030313, 2025).
pneumonia (1 paper, 2015). An acute, acute and chronic, or chronic inflammation focally or diffusely affecting the lung parenchyma, caused by an infection in one or both of the lungs (by bacteria, viruses, fungi, or mycoplasma.). "Compared to children with normal x-ray, children with end-point pneumonia had significantly higher C-reactive protein, procalcitonin and Chitinase 3-like-1, while those with other infiltrates had elevated procalcitonin and von Willebrand Factor and decreased soluble Tie-2 and endoglin." (PMID 26366571, 2015).
polycythemia (1 paper, 2023). Abnormally high mass or concentration of red blood cells in the blood, either due to an increase in erythropoiesis or a decrease in plasma volume. "This, however, supports the notion that a form a polycythemia is taking place in Endoglin-deficient zebrafish that puts the heart at stake." (PMID 37264878, 2023).
postherpetic neuralgia (1 paper, 2025). "ELISA results showed SNI intervention significantly inhibited endoglin expression, consistent with our findings in patients with postherpetic neuralgia (PHN)." (PMID 41030313, 2025). "Sequencing of peripheral blood from patients with postherpetic neuralgia (PHN) revealed a decreased level of endoglin." (PMID 41030313, 2025).
prostate tumor (1 paper, 2020). "Furthermore, endoglin-expressing CAFS were able to promote neovascularization and tumor growth, suggesting that endoglin on CAFs in prostate tumor mediates metastasis and tumor growth." (PMID 32059544, 2020).
pterygium (1 paper, 2021). A wedge-shaped fibrovascular lesion arising from the bulbar conjunctiva and extending to the cornea. "Compared with the conjunctiva, several key factors related to angiogenesis, such as PECAM1, CD34, VWF, and ENG, were highly expressed in the pterygium." (PMID 33790949, 2021). "Additionally, CD34, VWF, and ENG, endothelial cell surface markers, and their positive microvascular counts were markedly higher in pterygium than those in conjunctival tissue." (PMID 33790949, 2021).
renal tumor (1 paper, 2020). "To confirm the findings obtained in the autopsy samples, we also measured endoglin levels in eleven kidney biopsies from patients with DN; as a control, we stained tumor-free kidney samples from seven non-diabetic patients who underwent a renal tumor resection." (PMID 33081058, 2020).
septic shock (1 paper, 2014). Shock caused by infection; frequently caused by gram negative bacteria, although some cases have been caused by other bacteria, viruses, fungi, and protozoa; characterized by fever, chills, tachycardia, tachypnea, and hypotension. "Endoglin is an RGD membrane protein acting as transforming growth factor-β accessory receptor and has been implicated in leucocyte recruitment and extravasation and more recently in septic shock-induced disseminated intravascular coagulopathy." (PMID 24651155, 2014).
skin carcinoma (1 paper, 2019). "Endoglin is also expressed in cancer cells where it can behave as both a tumor suppressor in prostate, breast, esophageal, and skin carcinomas and a promoter of malignancy in melanoma and Ewing’s sarcoma." (PMID 31540324, 2019). "Notably, a similar role for endoglin as a tumor suppressor in breast, prostate, esophageal, and skin carcinomas has been described." (PMID 31540324, 2019).
spindle cell carcinoma (1 paper, 2012). "Expression of endoglin in a spindle cell carcinoma line suppressed Smad phosphorylation and tumorigenicity." (PMID 23326666, 2012). "Endoglin exists as a membrane bound form but is shed from the membrane at late stages of tumor progression in spindle cell carcinoma." (PMID 23326666, 2012). "Knockdown of endoglin in transformed keratinocyte cell lines not only enhanced TGFβ1 signaling, induced growth arrest and suppressed tumor formation, but also caused EMT, invasiveness and conversion to spindle cell carcinoma." (PMID 23326666, 2012).
stem cell leukemia (1 paper, 2020). "Downstream of Endoglin, Smad1 and the master hematopoietic regulator Scl (stem cell leukemia) were identified to mediate the observed effects of CD105 on BL-CFC and their erythroid/endothelial potential." (PMID 33287465, 2020).
vulvar cancer (1 paper, 2023).
tumor (564 papers, 2003 to 2026). "Of note, ENG (CD105) has been prominently shown to localise to the endothelium of tumour‐associated vasculature." (PMID 39790063, 2025). "This tumor-associated expression pattern has prompted a wide range of investigative efforts to study endoglin as a prognostic, imaging, and potential therapeutic target in cancer." (PMID 41039222, 2025). "As endoglin is abundantly expressed by tumor-associated vascular endothelium, monoclonal antibodies to endoglin have been used to treat cancer and to visualize tumor angiogenesis using imaging techniques." (PMID 41039222, 2025). "The crystal structure of the ENG in complex with its ligand bone morphogenetic protein 9 (BMP9) shows that the interface between ENG and BMP9 contains residues mutated in HHT1 and overlaps with the epitope of tumor-suppressing anti-ENG monoclonal TRC10540." (PMID 38589397, 2024). "A positive correlation was observed between tumor growth rate (measured on contrast-enhanced MRI) and vessel density based on endoglin staining, but only in NF2-associated VSs." (PMID 36844233, 2023). "Endoglin expression has also been reported in tumor-infiltrating Tregs, macrophages, cancer-associated fibroblasts, and cancer (stem) cells." (PMID 36147918, 2022). "In a multivariable Cox regression model that included established available preoperative variables (age, sex, and clinical tumor stage), a higher preoperative plasma level of endoglin was associated with worse RFS, CSS, and OS (all p < 0.001)." (PMID 34587660, 2022). "Endoglin has been found to be overexpressed in tumor-associated angiogenic vessels compared with normal vessels." (PMID 35409247, 2022). "The expression of VEGF-associated angiogenic indicators (VEGF and Endoglin) and the tumor marker carcinoembryonic antigen (CEA) was also determined for a mechanistic study." (PMID 34235153, 2021). "Endothelial cells of these vessels express CD105 (endoglin), an activation marker characteristically expressed in tumour-associated vasculature, which suggests ongoing neoangiogenesis." (PMID 34282761, 2021). "On the other hand, the preoperative serum levels of endoglin in patients with endometrial carcinoma show poor performance as a diagnostic marker of tumor metastasis." (PMID 34501347, 2021). "Weighted Gene Co-expression Network Analysis (WGCNA) identified several modules strongly associated to tumour endothelial cells or angiogenic activated endothelial cells with high endoglin (ENG) expression." (PMID 33917186, 2021). "As in physiologic angiogenesis, most studies examining the role of endoglin in tumor angiogenesis use endoglin-deficient mice." (PMID 33800564, 2021). "Regarding cancer development, other authors have shown that endoglin deficiency or different anti-endoglin treatments reduce the vascularity of tumors and, therefore, decrease tumor growth." (PMID 31897911, 2020). "Among these, αβ integrins 60, 61, VEGR-VEGFR-2 62, endoglin 63, and nucleolin 64 have been successfully studied to target NPs to tumor associated endothelium." (PMID 32373218, 2020). "Recent studies have shown that IMVD assessed by detection of Endoglin (CD105) is more specifically associated with tumor neovascularization and represents a significant prognostic marker in several tumors." (PMID 29304781, 2018). "The results indicated that the overexpression of ENG protein in tumor microvessels was significantly associated with poor DFS in patients with cancer (HR = 3.23, 95% CI 2.10–4.95, P < 0.001)." (PMID 29484142, 2018). "The deficiency of even a single copy of the endoglin gene in ECs leads to increased metastatic capability due to the weakened EC barrier to tumour cell intra- and extravasation." (PMID 30563158, 2018). "The role of endoglin in tumour-associated angiogenesis, as well as recent tests of anti-endoglin therapies, need to be briefly related to two other pro-angiogenic factors which are closely associated with ECs activation." (PMID 30563158, 2018).